LGR5 (leucine rich repeat containing G protein-coupled receptor 5)
Diseases named in the same sentence as LGR5 in open-access papers (continued):
Sharing a sentence is not in itself a finding about the gene and the disease.
cancer (continued). "As one of the Wnt target genes, LGR5 expression has been associated with abnormally enhanced Wnt signaling in many different types of cancers." (PMID 34493772, 2021). "In the present study, loss of PTEN in FTE led to the enrichment of cancer stem cell markers such as LGR5, WNT4, ALDH1, CD44." (PMID 33828085, 2021). "These carcinomas and their onset are associated with the impairment of intestinal cell homeostasis, which is regulated by a balanced number of Paneth cells and Lgr5 expressing intestinal stem cells (Lgr5+ ISCs)." (PMID 34129057, 2021). "The antrum contains the majority of Lgr5+ stem cells targeted for our mutations, yet cancer incidence was strikingly higher in the SCJ." (PMID 31901081, 2020). "The leucine-rich repeat-containing G-protein coupled receptor 5 (LGR5) is a Wnt/β-catenin target gene implicated in cancer cell proliferation and migration." (PMID 33080952, 2020). "Using patient-derived CRC organoids, we show that MEK inhibition leads to increased Wnt activity, elevated LGR5 levels and enrichment of gene signatures associated with stemness and cancer relapse." (PMID 31097693, 2019). "Overexpression of Lgr5 was not only associated with chemo-resistance but also with metastasis and cancer stage." (PMID 31814939, 2019). "One putative target gene identified in our cohort was LGR5—a downstream target of WNT pathway activation that has been implicated in promoting a cancer stem cell (CSC) phenotype in GBM." (PMID 29428975, 2018). "Of the 82 unique prognostic biomarkers identified, meta-analyses showed prominent biomarkers, including COX-2, PAK-1, p14ARF, PD-L1, MET, LC3B, IGFBP7 and LGR5, associated to each hallmark of cancer." (PMID 30185893, 2018). "Of the 82 unique prognostic biomarkers identified, meta-analyses showed several promising biomarkers, including COX-2, PAK-1, p14ARF, PD-L1, MET, LC3B and LGR5, associated to each hallmark of cancer feature." (PMID 30185893, 2018). "In the case of cancer, LGR5 expression is associated with increased cell proliferation and decreased apoptosis." (PMID 27979825, 2017). "The cancer stem cell marker LGR5 is associated with immune-related TME." (PMID 41194856, 2025). "LGR5 is also associated with methylation abnormalities in cancer." (PMID 38787285, 2024). "As in the colon LGR5 has been associated with cancer, in this case, gastric adenocarcinomas." (PMID 38903529, 2024). "In addition to MMPs, there was higher expression of Foxc2, a transcription factor associated with EMT and cancer metastasis, and stemness marker Lgr5." (PMID 37581937, 2023). "However, current studies have shown that the effect of cancer‐associated fibroblasts on LGR5+ stem cells varies in different studies." (PMID 37578396, 2023). "Because LGR5 may have different properties than other cancer stem cell markers, there is an association between low LGR5 expression in fat invasion and cancer-associated adipocytes, especially CCL2, which may result in EMT." (PMID 35123536, 2022). "The R-spondin/LGR5/RNF43 module has also been implicated in Wnt signaling driven cancers." (PMID 34552611, 2021). "Intrinsic factors such as stem cell markers (i.e., LGR5) and extrinsic factors including the surrounding microenvironment (e.g., bacterial and toxic drivers of mutagenesis and cancer associated fibroblasts supporting cancer growth) contribute to hepatocellular carcinoma growth." (PMID 33807722, 2021). "Thus, cancer-driven cell competition induces a cell-state transition in the surrounding WT epithelium that is characterized by loss of LGR5+ stem cells and adoption of a fetal-like state." (PMID 34233177, 2021). "Overall LGR5 cancer positivity is generally associated with the basal LGR5 expression levels in each organ, as the stomach and breast show very little or no LGR5 expression in normal tissues, whereas the colorectum has a greater number of LGR5 cells at the base of the crypts." (PMID 34493772, 2021).
cancer (continued). "Transcription factor genes (OCT4, KLF4, SOX2, MYC, NANOG, and REX1) and cell surface markers (CD133, LGR5), which are associated with embryonic stem cells, induced pluripotent stem cells, and cancer stem cells, have been selected for measuring expression levels from the selected tissues." (PMID 34452555, 2021). "An earlier study suggested that stromal staining of LGR5 could be associated with cancer with an advanced stage of CRC." (PMID 32671503, 2020). "Moreover, some studies suggest that the degree of cancer differentiation (grading) is also highly associated with Lgr5 expression." (PMID 32671503, 2020). "We hypothesize that LGR5, an established CSCs marker in several cancers including BC, can be used to identify at-risk BC patients that would benefit from treatment and can also serve as a therapeutic target for high-grade ER− BC lesions." (PMID 32522170, 2020). "Lgr5-associated signaling pathways may play different or even opposing roles in different cancer types." (PMID 31358061, 2019). "LGR5 has also been implicated in the chemotherapy resistance of various cancers, as well as in GC." (PMID 31827644, 2019). "Furthermore, it has been reported that Lgr5 overexpression is associated with resistance to chemotherapy in these cancer types." (PMID 31417548, 2019). "Furthermore, the NP-Dvl3 enhanced the LGR5 promoter activity to upregulate LGR5 expression, which was associated with increased cancer stemness in HCC." (PMID 28455968, 2017). "LGR5 deficiency was reported to deregulate the Wnt pathway and contribute to cancer." (PMID 22509329, 2012). "However, prolonged activation of Wnt/LGR5 by milk exosomes beyond the postnatal lactation period may increase the risk of Wnt-driven cancers." (PMID 40799516, 2025). "Additionally, oncogenic mutations could drive Lgr5-positive cancer cells from enterocyte or secretory precursor dedifferentiation toward a stem-like state." (PMID 39456736, 2024). "Thus, targeted therapeutic modulation of Lgr5-associated signaling pathways may provide potential opportunities for anti-cancer therapy." (PMID 31358061, 2019). "Research on the cancer stem cell marker leucine-rich repeat-containing g-protein coupled receptor 5 (LGR5) has shown that its deletion inhibits β-catenin nuclear translocation and downregulates c-myc/cyclin D expression, leading to ΔΨm collapse and apoptosis." (PMID 41567244, 2026). "The biobank was used to screen over 500 bispecific antibodies, leading to the identification of MCLA‐158, which is a therapeutic that selectively eliminates LGR5+ cancer stem cells while sparing healthy cells and inhibits metastasis." (PMID 41503026, 2026). "Tumorigenesis appears to be driven by LGR5+ cancer stem cells (CSCs) and the hyperproliferation of TA cells as colonocytes undergo metabolic reprogramming." (PMID 41002393, 2025). "Several articles were mainly published in journals related to cell biology and oncology, indicating that LGR5 plays a vital role in biological processes and cancer progression." (PMID 41194856, 2025). "using a syngeneic transplantation model of CRC organoids revealed that, based on scRNA-seq analysis, Lgr5+ cancer stem cells are divided into actively proliferating and quiescent populations, with the latter found to specifically express p57." (PMID 41346579, 2025). "This review outlines the role of LGR5 in the growth and metastasis of colorectal and other cancers, as well as the discovery and development of petosemtamab." (PMID 40427162, 2025). "α-LGR5 fills the need for an effective reagent to detect low LGR5 expression in certain stem cell compartments and overexpression in cancer cells." (PMID 40405910, 2025). "Our results showed that ALDH1, CD44, Sox2, Olig2, BMI1, LGR4, LGR5, Integrin α6, L1CAM, and ABC transporter associated with cancer stem cells were significantly downregulated." (PMID 39721005, 2025).
cancer (continued). "LGR5, as a well-recognized stem cell marker, exhibits diverse expression patterns and functional roles across different cancer types." (PMID 41194856, 2025). "α-LGR5 was extensively validated for a variety of research applications and detects cancer types with high levels of LGR5 (LGR5+ cells) - CRC (>80% of cases) and HCC (>90% of cases)—relative to healthy tissues that express low levels of the protein." (PMID 40405910, 2025). "Petosemtamab (MCLA-158) is a human, common light-chain IgG1 bispecific antibody that simultaneously targets the EGFR and the leucine-rich repeat-containing G-protein-coupled receptor 5 (LGR5), a cancer stem cell marker." (PMID 41375018, 2025). "Three cancer types—CRC, HCC and pre-B ALL—emerge as prime indicator cancers for novel LGR5 immunotherapeutics." (PMID 40405910, 2025). "In summary, these novel findings highlight the inherent heterogeneity of Lgr5+ cancer stem cells and underscore the necessity for novel therapeutic strategies targeting quiescent CCSCs to eradicate CRC." (PMID 41346579, 2025). "Preclinical studies road-testing the various α-LGR5-based modalities established potent and safe elimination of LGR5-expressing cancer cells in vitro and efficacy in a mouse model of human cancer in vivo." (PMID 40405910, 2025). "In this study, Lgr5+ cancer stem cells induced high OX40 expression and subsequent protumor signaling in ECs through paracrine EGF." (PMID 40026246, 2025). "These cancer driver cells express the leucine-rich G repeat-containing protein-coupled receptor 5 (LGR5) at the cell surface." (PMID 40427162, 2025). "Concordantly, the expression of cancer stemness-related genes, such as LGR5 and CD44, was significantly reduced at the mRNA and protein levels in TetOff cells upon expressing wt-Cdx1/2." (PMID 40399276, 2025). "Expression levels of cancer stem cell (CSC) marker genes Lgr5, Smoc2, Axin2, Rnf43, and CD44 were markedly reduced in Prrc2a‐deficient tumors induced by AOM‐DSS treatment." (PMID 39582289, 2025). "This review focuses on the role of LGR5 in cancer biology, experiments leading to the selection of the EGFR×LGR5 BsAb petosemtamab as having the most potency, and its unique mechanisms of action." (PMID 40427162, 2025). "The potential for LGR5+ stem-cell-like cells to both drive cancer growth and mediate treatment resistance has fueled increasing interest in targeting LGR5 therapeutically." (PMID 40427162, 2025). "Petosemtamab targets both EGFR as well as leucine-rich repeat-containing G-protein coupled receptor 5 (LGR-5), which is known to be upregulated in cancer and is also pro-oncogenic by encouraging cell proliferation and reducing apoptosis." (PMID 40868227, 2025). "Combining EGFR pathway inhibition with an LGR5-targeted approach more effectively treats cancer growth in a wide range of preclinical murine and human model systems." (PMID 40427162, 2025). "In contrast, miR-22 knockout mice showed attenuated Wnt/β-catenin activity and LGR5+ cancer stem cell penetrance." (PMID 40799516, 2025). "Although neoadjuvant therapy is effective, pathological examination of residual tumors has revealed the presence of small clusters of LGR5-positive cancer cells in the fibrous tissue." (PMID 40537472, 2025). "Despite the relatively smaller number of cells in the ‘CD44_high’ cluster, CD44 expression, along with other cancer stem cell marker genes such as LGR5, ALDH1A1, and FUT4, was significantly higher compared to the ‘CD44_low’ cluster." (PMID 40849307, 2025). "For example, Lgr5, a G protein-coupled receptor containing leucine-rich repeat sequences, is highly expressed in different types of cancers and is a unique marker for CSCs." (PMID 40003899, 2025). "These cells express specific surface markers such as CD133, CD44, and Lgr5, and exhibit potent tumorigenicity, drug resistance, and metastatic potential compared to conventional cancer cells." (PMID 41346579, 2025).
cancer (continued). "Among these, they identified MCLA-158, an EGFR × LGR5 bispecific antibody, that selectively degraded EGFR in LGR5+ cancer stem cells while sparing healthy tissues." (PMID 40843351, 2025). "Overall, it appears that the 3 SW480 subpopulations reflect distinct aspects of the cancer stem cell phenotype: the LGR5+ resident CSCs represented by the spheres, the EpCAMlo mCSCs, and the EpCAMhi HRCs." (PMID 39246444, 2024). "Few studies examined targeting Lgr5-positive cells in treating cancer and showed promising efficacy of antibody–drug conjugates against Lgr5-high gastrointestinal tumors." (PMID 38338736, 2024). "In a similar manner to the PAF1 knockdown, CDC73 or CTR9 knockdown inhibited cell proliferation, reduced the expression levels of most cancer stem cell marker genes including LGR5 and ID1, and increased those of KRT20 and MUCs." (PMID 38182897, 2024). "MCLA-158, a bAb that specifically triggers epidermal growth factor receptor degradation in LGR5+ cancer stem cells but shows minimal toxicity toward healthy LGR5+ colon stem cells, was tested in a large-scale functional screen." (PMID 38638528, 2024). "It has been demonstrated that NEDD4 and NEDD4L KO in IECs regulated Lgr5 degradation to mediate Wnt signaling and cancer development in APCmin mice." (PMID 39688910, 2024). "Taken together, we show that α-LGR5 can not only be used as a research tool and a biomarker but also provides a versatile building block for a highly effective immune therapeutic portfolio targeting a range of LGR5-expressing cancer cells." (PMID 39169164, 2024). "Crucially, expression of UBE2A mutants reduced the expression levels of most cancer stem cell marker genes including those of LGR5 and ID1 and increased those of KRT20 and MUCs." (PMID 38182897, 2024). "VTD effectively targets sorted CD44 + and LgR5 + positive stem cells, which strictly defines cancer stem cells in CRC." (PMID 39502780, 2024). "Here, we report for the first time that the metastasis inducer MACC1 transcriptionally regulates LGR5 expression to promote cancer stem cell properties in CRC by using 2D and 3D cell culture models, CRC-PDX mouse models as well as human CRC patient samples." (PMID 38339354, 2024). "LGR5 is closely related to the regulation of Wnt/β‐catenin signaling and also plays an important role in the regulation of cancer stem cell (CSC) function." (PMID 38787285, 2024). "For CRC, we directly compared LGR5 expression levels in three individual biopsies each containing regions of healthy colon epithelia, dysplastic epithelia and cancer." (PMID 39169164, 2024). "On the other hand, upon YAP1/TAZ activation, genes within the Wnt signaling pathway were suppressed in the RE cells, which is similar to the changes in YAP1-dependent reprogramming of LGR5+ stem cells during intestinal regeneration and cancer." (PMID 38540020, 2024). "LGR5+ cells depend on ligands from their niche to determine cell fate, contributing to either regular tissue turnover, regeneration after injury or even cancer progression." (PMID 38903529, 2024). "As Lgr5+ cells are overexpressed in various cancer types and constitute an important component of the TME, they are probably related to immune CYT." (PMID 38612436, 2024). "While we have established CRC, HCC and pre-B-ALL as priority cancer targets for α-LGR5-based therapeutics, future studies will determine other targetable cancer types by increased LGR5 protein levels as a prognostic marker." (PMID 39169164, 2024). "Specifically, Lgr5 has been highlighted as a novel biomarker in various human cancers, promoting CSC proliferation and self-renewal via the Wnt/β-catenin pathway." (PMID 39769068, 2024). "Taken together, MACC1 promotes cancer stem cell-like properties in CRC via employment of LGR5 as a novel signaling mediator." (PMID 38339354, 2024).
cancer (continued). "The high LGR5 expression levels specific to certain malignancies, rapid internalisation kinetics of α-LGR5 and LGR5 trafficking to the lysosome raised the intriguing prospect of targeting cancers using α-LGR5-based antibody-drug conjugates (ADCs)." (PMID 39169164, 2024). "Since MACC1 is decisive for metastasis induction, the importance of the stemness gene LGR5 in cancer metastasis is crucial to extract." (PMID 38339354, 2024). "High expressions in EPHB2 and LGR5 signature cancer stem cells and low expressions on late transit amplifying colonic crypt genes were detected in RSS2." (PMID 38532103, 2024). "The ongoing advancements in this field promise to enhance further investigations and progress, laying the groundwork for future research on the regenerative properties of LGR5 stem cells, cancer treatment, and drug development." (PMID 38903529, 2024). "It has been difficult however, to fully assess LGR5 as a therapeutic target for the treatment of cancer due to the scarcity of specific, high-affinity antibodies against human LGR5." (PMID 39169164, 2024). "Advancements in understanding LGR roles, such as Lgr5, Lgr4, and Lgr6, hold therapeutic potential in regenerative medicine and cancer therapy." (PMID 39239558, 2024). "Our cell expression data establishes pre-B-ALL, CRC and HCC cellular models for LGR5-expressing cancer cells." (PMID 39169164, 2024). "In vivo ablation of the tumor-resident Lgr5+ cancer stem cell pool has revealed a role for these cells in cancer initiation and maintenance, as well as metastasis." (PMID 39191487, 2024). "The interplay between CYT and Lgr5+ cells within the TME can present a new chapter in cancer management." (PMID 38612436, 2024). "The contribution of cancer stemness factors, such as LGR5 to various chemotherapeutics, including 5-FU and doxorubicin via WNT signaling, has been demonstrated extensively." (PMID 39580452, 2024). "We confirm the highly dynamic nature of LGR5 protein internalisation and lysosomal trafficking in cancer cells." (PMID 39169164, 2024). "This pattern extends to the cancer stem cell biomarkers LGR5 and the transcription factor c-MYC, which are universally associated with cancer stem cells (CSCs)." (PMID 38339195, 2024). "The regulator of the canonical Wnt pathway, leucine-rich repeat-containing G protein-coupled receptor 5 (LGR5), is expressed in the stem cell compartment of several tissues and overexpressed in different human carcinomas." (PMID 39769183, 2024). "Lgr5 is also highly expressed in various cancer tissues and enhances tumorigenesis, cancer cell mobility, and EMT in breast cancer cells by activating multiple pathways, such as Wnt/β-catenin and Notch signaling." (PMID 38164743, 2023). "Meanwhile, LGR5 has been reported to be a biomarker for both adult stem cells and cancer stem cells (CSCs) in the gastrointestinal tract." (PMID 38136437, 2023). "In experimental settings, a landmark study found that LGR5 cancer stem cells are unnecessary for primary CRC growth but required for metastasis formation." (PMID 37627048, 2023). "There was a decrease in expression of a number of anti-cancer genes (e.g., Casp3, Mgmt, Parp1, Ptpn11) as well as an increase in several cancer-promoting genes (e.g., Ly6a, Lgr5, Vnn1)." (PMID 38151490, 2023). "To confirm the binding profile difference of monovalent and bivalent RSPO2 furin domain forms, we examined the binding of the two forms on cancer cell lines that express either LGR4 or LGR5 endogenously." (PMID 37402772, 2023). "Very impressively, we found high frequency of CAFs marked by alpha‐smooth muscle actin (α‐SMA) surrounding LGR5 expressing cancer cells in primary liver tumor." (PMID 37578396, 2023). "DCA also activates β-catenin signaling and drives malignant transformations in Lgr5-expressing (Lgr5+) cancer stem cells for CRC growth and invasiveness." (PMID 36830830, 2023).